ALB (albumin)
Diseases named in the same sentence as ALB in open-access papers (continued):
Sharing a sentence is not in itself a finding about the gene and the disease.
acute kidney injury (continued). "In an unconditional logistic regression analysis, renal failure, CRP, PCT, albumin, leucocytes, and the PCT/albumin ratio at admission were significantly associated with urosepsis." (PMID 29995751, 2018). "Of note, a recent single-center, double-blind, randomized, controlled trial of albumin administration for a serum albumin level of less than 4.0 g/dL prior to OPCABG revealed a significant decrease in stage 1 acute kidney injury in the albumin group." (PMID 29075482, 2017). "Albumin infusions were found to reduce the incidence of renal failure and mortality in patients with SBP." (PMID 29041907, 2017). "Our results show that although healthy smokers possess higher [Met(O)]/[Met] with respect to Met-111 or Met-147 of serum albumin, the magnitudes of the increases in healthy smokers are less than those in diabetic and renal failure patients." (PMID 27929071, 2016). "Urine albumin levels are increased in both glomerular and tubular diseases, but recently it was reported that the gene expression of albumin is increased in acute kidney injury, thus making it a sensitive marker for acute kidney injury." (PMID 25970334, 2015). "In some patients with renal failure, the fractional abundance of S-cysteinylated albumin has been reported at over 50%, although these studies lacked detailed documentation of sample-handling conditions." (PMID 26181416, 2015). "Our study findings were probably due to the effect of other factors such as proteinuria, which is frequent among renal failure patients, on serum albumin level." (PMID 25032136, 2014). "It has been reported that survival after acute kidney injury is significantly altered according to the level of serum albumin." (PMID 25074590, 2014). "A significant reduction of SVRI after plasma-expansion with hyperoncotic albumin in cirrhotic patients with renal failure has been described before." (PMID 24467993, 2014). "Albumin is a plasma expander that increases cardiac preload and peripheral vascular resistance, attenuates endothelial dysfunction, reduces renal failure, and improves survival." (PMID 24222902, 2013). "Proteinuria and albuminuria, even an increased urinary albumin-creatinine ratio (UACR) within the normal range, have also been shown to be associated with the development of both renal failure and CVD." (PMID 24265736, 2013). "Acute renal failure due to low serum albumin and overestimate diuretic consumption in other centers were seen in eight patients (18%)." (PMID 20436726, 2009). "Plasma expansion with albumin has been found to protect against renal failure in spontaneous bacterial peritonitis." (PMID 18752670, 2008). "The findings included a pathological urinary sediment, increased excretion of albumin and/or transferrin and/or glomerular antigens, and in three of them renal failure was also more prevalent." (PMID 16354301, 2005). "We investigated the clinical characteristics and risk factors of toxic kidney injury in highland areas using the acute kidney injury criteria defined by the kidney disease improving global outcomes work group, with focus on the significance of the fibrinogen- to- albumin ratio." (PMID 41525262, 2026). "The lower the albumin levels, the higher the risks of acute kidney injury and subsequent mortality." (PMID 40108938, 2025). "Albumin, serving as a critical component in maintaining plasma colloid osmotic pressure, plays a pivotal role in regulating fluid balance and tissue perfusion, thereby mitigating the progression of acute kidney injury." (PMID 40530353, 2025). "However, few studies have examined the usefulness of vitamin E‐coated dialyzers on reduced albumin in the context of dialysis therapy for acute kidney injury." (PMID 40108938, 2025). "The serum uric acid/albumin ratio (UAR), comprising serumuric acid and serum albumin levels, has emerged as a novel inflammatory biomarkerfor predicting the onset of AKI and is associated with short-term mortalityin patients with acute kidney injury." (PMID 40026514, 2025).
acute kidney injury (continued). "Significant albuminuria (defined as 30 mg or more of urinary albumin excretion per gram of creatinine on a random specimen) is an independent risk factor for ESKD, acute kidney injury (AKI), GFR loss, cardiovascular events, as well as cardiovascular and all-cause mortality." (PMID 38273240, 2024). "RAR, which represents the levels of RDW and albumin by organically combining the two, serves as a prognostic indicator for multiple diseases, including acute pancreatitis, cardiovascular disease, burn surgery, and acute kidney injury." (PMID 38877408, 2024). "As an example, the REDUCE Score incorporates comorbidities (COPD, congestive heart failure, renal failure) and blood parameters (hemoglobin, albumin) and takes prior ED visits (in the past 90 days) into account to highlight cancer patients at increased risk for side effects and ED visits." (PMID 39414641, 2024). "Additionally, among the nonsurvivors during hospitalisation, we observed a higher rate of acute kidney injury/acute renal failure; lower haemoglobin, albumin and bicarbonate levels; and higher age, creatinine levels and SOFA scores." (PMID 39357986, 2024). "However, current results are in line with previous animal studies indicating the enhancing effects of ginger on serum levels of albumin in acute kidney injury rats." (PMID 37228303, 2023). "However, there is still a critical unmet need for studies that guide albumin and vasopressor dosing and predict reversibility of renal failure after liver transplant." (PMID 37510105, 2023). "Other adverse effects included bleeding, hemolysis, decreased fibrinogen that required fresh frozen plasma transfusion, hypersensitivity to albumin, cardiac complications, and acute renal failure, which presented as elevated blood urea nitrogen (BUN) and hypokalemia." (PMID 37400755, 2023). "Urinary albumin to creatinine ratio (ACR) has been used as the preferred indicator for quantifying albuminuria in terms of biochemical values and included in the indicators for assessing the risk of renal failure." (PMID 36901874, 2023). "However, acute kidney injury developed in 21 patients in the cefotaxime group, but only in 6 patients in the albumin group (10 %) (p = 0.002)." (PMID 37218881, 2023). "Models incorporating albumin are challenged primarily due to missing values in retrospective cohorts, variable cut-off levels, and correlation with other conditions (e.g., previous/concomitant cancers, renal failure, low BMI, inflammatory diseases)." (PMID 37833260, 2023). "A biochemical study assured us that an acute inflammatory process with a typical decrease in albumin level, and an increase in Fi as one of the reactants of the acute phase of inflammation, was accompanied by the development of renal failure with an increase in blood plasma creatinine." (PMID 36551818, 2022). "The results showed that alkaline phosphatase, MCV, acute renal failure, and digoxin increased the mortality of patients with hypertensive chronic kidney disease, while insurance, albumin, MCHC, coronary angiogram, hyperlipemia, and kidney surgery decreased the mortality." (PMID 35600047, 2022). "Both DFO and DFX can cause increases in serum Cr, proteinuria, and even renal failure.The results of this study reveal that the BUN level and urinary Ca/Cr, UA/Cr, and albumin/Cr ratios were significantly higher, while the serum Ca and UA levels were significantly lower in patients on DFO therapy." (PMID 36258980, 2022). "Mortality in CDI patients might be related to age, albumin levels, leukocytes count and renal failure." (PMID 34204307, 2021). "Additional research is needed to determine whether urinary albumin excretion is increased by vascular endothelial dysfunction due to oxidative stress induced by the renal failure." (PMID 34940691, 2021). "However, olmesartan treatment improved several renal failure parameters, including urinary albumin excretion." (PMID 34413390, 2021).
acute kidney injury (continued). "While investigations on the mediastinal mass were being performed, the patient developed acute kidney injury (Creatinine 4.7 mg/dL), with nephrotic syndrome: serum albumin was 9.7 g/L, proteinuria was 17 g/g (composed of more than 80% of albumin) and microscopic hematuria was positive." (PMID 34493204, 2021). "It is known that serum albumin decreases in patients with renal failure." (PMID 34840504, 2021). "However, the urinary albumin excretion level, which is a biomarker for acute kidney injury, was similar in the CN-W and LP-W offspring, but tended to be higher in the LP-S than the CN-S offspring." (PMID 30301128, 2018). "A 53-year old woman presented with albumin–predominant moderate proteinuria and renal failure." (PMID 30419839, 2018). "This protocol describes the RCT which will determine if administering daily 20% HAS infusions in order to increase serum albumin to near-normal levels after admission to hospital will reduce rates of infection, renal failure and death in patients with decompensation of liver cirrhosis." (PMID 30344180, 2018). "Although serum cystatin C (sCysC), urinary N-acetyl-β-d-glucosaminidase (uNAG), and urinary albumin/creatinine ratio (uACR) are clinically available, their optimal combination for acute kidney injury (AKI) detection and prognosis prediction remains unclear." (PMID 28264714, 2017). "Fluid resuscitation with colloids (albumin and hydroxyethyl starch) should not be used as they can cause acute kidney injury, coagulopathies and compromised graft function." (PMID 28926566, 2017). "Albumin administration in cardiac surgery was associated with a dose-dependent risk of acute kidney injury, whereas 6 % HES 130/0.4 was not." (PMID 26768898, 2016). "We could have used albumin, but even albumin can promote renal failure, as has been shown in a recent study in cardiac surgery." (PMID 27671340, 2016). "However, this unique model largely avoided the effects of renal failure and severe alteration of renal hemodynamic besides albuminuria itself and permitted us to clearly study the actions of urinary albumin on renal transporter expression." (PMID 27323402, 2016). "If this point is further proven in prospective randomized clinical trials it means that these patients can easily be managed with a lower dose of albumin without putting them at increased risk of renal failure." (PMID 26150850, 2015). "Whether a high or low SIG value correlates with mortality in patients with metabolic acidosis and acute renal failure depends on the serum levels of creatinine, chloride, albumin, and phosphate." (PMID 25162029, 2014). "However, in a large meta-analysis, the authors reported that hyperoncotic albumin decreased the odds of acute kidney injury and death by 76% and 48%, respectively." (PMID 25474401, 2014). "Patients with either short or long sleep durations may be considered to have a high risk for both renal failure and CVD, given that increased urinary albumin excretion is a strong risk factor for these diseases." (PMID 24265736, 2013). "Further predictive factors associated with a poor prognosis included shock upon admission, pre-operative metabolic acidosis, tachycardia, elevated respiratory rate, acute renal failure, low serum albumin level, high ASA score, and a pre-operative time-delay >24 hours." (PMID 23574922, 2013). "Other authors have reported that, in the absence of exogenous UII, palosuran potentiated glucose-induced insulin release in perfused rat pancreas and decreased 24-hour urinary albumin excretion rate in diabetic patients with renal failure with regard to their disease progression." (PMID 21559414, 2011). "Pre-albumin is a useful parameter for monitoring, re-nutrition and the evolution of nutritional status of the seriously ill patient and is the only valid parameter for evaluation of the nutritional status in renal failure." (PMID 22163211, 2011).
acute kidney injury (continued). "• Hyperoncotic albumin decreased the odds of acute kidney injury by 76% and of death by 48%." (PMID 21029460, 2010). "The recurrent group also had significantly lower serum albumin levels and platelet counts, as well as higher rates of acute kidney injury (AKI), serum creatinine, serum bilirubin, prothrombin time, and MELD score compared to the non-recurrent group." (PMID 41353185, 2025). "This study aimed to investigate the association between the neutrophil percentage-to-albumin ratio (NPAR) and the occurrence of acute kidney injury (AKI) in patients with severe ischemic stroke." (PMID 41036272, 2025). "This study aimed to evaluate the association between the red cell distribution width-to-albumin ratio (RAR) and the early onset of Acute Kidney Injury (AKI) in patients diagnosed with acute pancreatitis (AP)." (PMID 41054085, 2025). "In addition, nutritional biomarkers such as albumin and prealbumin may be significantly affected by renal failure, liver failure, cardiopulmonary bypass, and intravenous albumin use, which are common in this population." (PMID 41305659, 2025). "The plasma uric acid/albumin ratio (UAR) has emerged as a novel inflammatory biomarker for predicting the development of acute kidney injury (AKI) following percutaneous coronary intervention." (PMID 40026514, 2025). "We assessed albumin utilization patterns across racial and ethnic groups and payor types, and their overall impact on acute kidney injury (AKI)-related hospitalization using an adjusted generalized linear model (aGLM)." (PMID 41021268, 2025). "Hemodiafiltration (HDF) with (V‐RATM) and without a vitamin E‐coated hemodiafilter (ABHTM) was performed in an acute kidney injury pig model to determine whether changes in the serum albumin, the oxidized albumin (OxiALB), and the reduced albumin (RedALB) levels differ between the two groups." (PMID 40108938, 2025). "Renal replacement therapy (RRT) for acute kidney injury (AKI), albumin dialysis, or plasma exchange for acute-on-chronic liver failure (ACLF) or acute liver failure (ALF) can be used to temporarily support failing organs." (PMID 39737068, 2024). "Urinary albumin-to-creatinine ratio (uACR) is the recommended measure for assessing albuminuria and has also been used to predict the risk of renal failure in CKD patients and it was included in the CKD staging system as well as in risk scores to predict the occurrence of renal failure." (PMID 39055699, 2024). "On the third day, the nephrology team was consulted due to acute kidney injury (AKI) and oliguria, marked by a rapid rise in the patient’s creatinine to 4.01, reduced albumin levels, and poor urine output." (PMID 39429409, 2024). "Concurrently, the patient’s serum creatinine rapidly increased to 456.36 μmol/L, indicating acute kidney injury (AKI), accompanied by hematuria and proteinuria (urine protein/creatinine ratio 2179.33 mg/gCr, albumin/creatinine ratio 594.81 mg/gCr)." (PMID 39722821, 2024). "Mortality risk was higher in overhydrated patients (OR: 6.2, 95% CI: 1.2–32.6, p = 0.02) and in persistently overhydrated patients (OR: 9.57, 95% CI: 1.18–77.5, p = 0.03) even after adjustment to age, serum albumin and acute kidney injury (AKI) in stages 2–3." (PMID 38256674, 2024). "There are relatively few articles on the relationship between serum albumin and acute kidney injury (AKI)." (PMID 36836115, 2023). "The results of our own research also exposed the fact that, after excluding patients with liver or renal failure features from the study, in 86% of patients, the parameter was below the norm threshold, with 37.2% below 25 g/L, and only 14% of the studied patients obtained the correct albumin level." (PMID 35010870, 2022). "The results showed that eGFR remained strongly associated with renal failure in the dynamic model compared with the baseline static model, but other variables, such as male sex, serum phosphorus, albumin (ALB), and bicarbonate levels, were no longer significant." (PMID 34300251, 2021).
acute kidney injury (continued). "Acute kidney injury (AKI) should be treated with volume expansion with albumin and withdraw from diuretics and beta-blockers." (PMID 34640424, 2021). "Besides a triad consisting of fever, hepatosplenomegaly, and cytopenia (62% of our patients), patients presented with renal failure, liver dysfunction (i.e., elevated bilirubin, low albumin, coagulation disorder), neurological symptoms (impaired consciousness, seizures), or bleeding complications." (PMID 32076823, 2020). "Nephrology referrals are recommended for patients with estimated glomerulofiltration rate (eGFR) <30 ml/min/1.73 m2, abrupt sustained fall in eGFR (Acute Kidney Injury – AKI), albumin to creatinine ratio of >300 mg/gm." (PMID 28629462, 2017). "In addition, HGS measurement was a better prognostic marker of renal failure than albumin." (PMID 25695027, 2014). "In groups without renal failure, low creatinine and albumin levels might be associated with a nutritional disorder or other comorbid inflammatory-infectious status." (PMID 23878538, 2013). "Therefore, the purpose of this study is to investigate the relationship between acute kidney injury (AKI) and the lactate-to-albumin ratio (LAR) in patients hospitalized for PE." (PMID 41901556, 2026). "Notably, a meta-analysis has shown that resuscitation using macromolecular solutions is associated with increased mortality and acute kidney injury (AKI); nevertheless, better clinical outcomes have been reported in patients treated with hyperoncotic albumin." (PMID 39792932, 2025). "The findings suggest that albumin infusion confers significant benefits in reducing the incidence of post-paracentesis circulatory dysfunction (PICD), acute kidney injury (AKI), and hyponatremia, while also improving survival in selected patient populations." (PMID 41140983, 2025). "Significant factors predicting recurrent SBP included acute kidney injury, elevated CRP levels, low serum albumin levels, high serum bilirubin levels, reduced β-blocker use, increased proton-pump inhibitor use, and a higher MELD Score (odds ratio > 1 for all)." (PMID 41353185, 2025). "These factors comprise age, septic shock, acute kidney injury, metabolic acidosis, neoplasm, BUN, CRP, and albumin." (PMID 39103964, 2024). "In another retrospective cohort study, incidences of acute kidney injuries and fatality were significantly lower in cirrhotic SBP patients treated with albumin in combination with antibiotics." (PMID 38551716, 2024). "The aim of this study was to investigate the prognostic role of platelet to albumin ratio (PAR) and in persistent acute kidney injury (pAKI) of patients admitted to the intensive care unit (ICU)." (PMID 37468887, 2023). "In patients with low albumin levels before CABG surgery,postoperative atrial fibrillation, acute kidney injury, slower recovery,readmission, and mortality rates were found to be high." (PMID 37403893, 2023). "In patients who are hemodynamically unstable or suffer from acute kidney injury (AKI), 8 g of albumin should be replaced for every liter of ascites, even if the amount of paracentesis is under 5 L. This is because the kidneys require stable hemodynamics to preserve their function." (PMID 37218881, 2023). "Management was commenced for a relapse of nephrotic syndrome and acute kidney injury (AKI) with increased steroid dosing and administration of intravenous diuretics and albumin." (PMID 37365496, 2023). "In agreement with the role of AKT in albumin reabsorption, it was observed that in a subclinical acute kidney injury animal, activation of AKT enhances PT albumin reabsorption, reduces proteinuria, and ameliorates tubule-interstitial injury." (PMID 35055044, 2022). "Nevertheless, the occurrence of renal failure (2.1 vs. 15.8%, p = 0.003) and pulmonary infection (5.3 vs. 15.8%, p = 0.042) was more common in high MELD-albumin group." (PMID 35845070, 2022).